TPD52L2 (TPD52 like 2)
Diseases named in the same sentence as TPD52L2 in open-access papers (continued):
Sharing a sentence is not in itself a finding about the gene and the disease.
tumor (10 papers, 2018 to 2025). "Elevated TPD52L2 expression was significantly associated with advanced Tumor, Node, Metastasis (TNM) stage and independently predicted reduced overall survival according to multivariate Cox regression." (PMID 40973691, 2025). "The results of multivariate analysis showed that TPD52L2, age, tumor grade were independent prognostic risk factors for ccRCC patients." (PMID 38074636, 2023). "Meanwhile, some scholars have also reported that TPD52L2 is involved in the pathological process of other tumor as a pathogenic gene." (PMID 38074636, 2023). "Univariate analysis revealed that TPD52L2, age, tumor grade, tumor stage, T, and M were prognostic risk factors for ccRCC patients." (PMID 38074636, 2023). "High TPD52L2 expression is a possible indicator of immune infiltration and associated with tumor immunosuppressive status in LUAD." (PMID 34744715, 2021). "The correlation between TPD52L2 expression and the infiltration level of immune cells, tumor mutational burden (TMB), and immunosuppressive genes was further evaluated in LUAD." (PMID 34744715, 2021). "Functional enrichment analysis of genes coexpressed with Xiantao-derived TPD52 and TPD52L2 revealed distinct tumor-related pathways." (PMID 40973691, 2025). "These pathways are involved in the invasion of tumor cells and immune regulation, indicating that the abnormally high expression of TPD52L2 plays an important role in the tumor progression and TME." (PMID 38074636, 2023). "Further, the proteomic sequencing data of 5 pairs of ccRCC tissue samples from our study were also analyzed, and the results showed the protein expression level of TPD52L2 in tumor tissues was still abnormally increased." (PMID 38074636, 2023). "Cell proliferation assays in vitro and tumor growth analysis in vivo were performed to determine the function of TPD52L2 during BLBC progression." (PMID 36071863, 2022). "This study revealed the potential role of TPD52L2 in tumor immunology and its prognostic value, which will propose a new target for tumor therapy." (PMID 34744715, 2021). "We further evaluated TPD52L2 expression in paired tumor and normal tissues and various tumor stages." (PMID 34744715, 2021). "In our study, we firstly assessed the expression of TPD52L2 and found TPD52L2 expression was higher in tumor tissues compared with normal tissues in LUAD." (PMID 34744715, 2021). "The results showed that TPD52L2 might regulate multiple tumor progression-related signaling pathways, such as the PI3K−Akt signaling pathway, IL−17 signaling pathway, Wnt signaling pathway, and Hippo signaling pathway." (PMID 38074636, 2023). "This implies that TPD52L2 may be a pathogenic gene for ccRCC, as it is generally accepted that TMN stage and grade are negatively correlated with the prognosis of tumor patients." (PMID 38074636, 2023). "In general, TPD52L2 may participate in the pathological evolution of ccRCC by regulating the malignant biological behavior and immune activity of tumor cells." (PMID 38074636, 2023). "We further examined whether TPD52L2 expression was correlated with pathological stage and pathological tumor (pT) status." (PMID 36071863, 2022). "Therefore, the correlation between TPD52L2 expression and tumor pathological stage supports our study on the growth- and metastasis-promoting effects of TPD52L2 in BLBC cell lines." (PMID 36071863, 2022). "In contrast, TPD52L2 was lowly expressed in tumor tissues of KICH and PRAD." (PMID 34744715, 2021). "Firstly, we explored the expression of TPD52L2 in 33 tumor types using TCGA and GTEx data." (PMID 34744715, 2021). "In addition, TPD52L2 expression was higher in relatively worse tumor stages in LUAD." (PMID 34744715, 2021). "Also, we validated targets like AHNAK, tumor-specific proteins like TPD52L2, TS101." (PMID 32974197, 2020). "Subsequently, clinical correlation analysis revealed that the expression level of TPD52L2 increased along with TNM stage and tumor grade." (PMID 38074636, 2023).
tumor (continued). "In addition, this study also attempted to explore the relationship between TPD52L2 and TMB, an important marker of tumor immunotherapy response." (PMID 38074636, 2023). "To date, there was no report about TPD52L2 gene fusion in the tumor, except for our case." (PMID 37735390, 2023). "In addition, TPD52L2 expression was higher in relatively worse tumor stages in adrenocortical carcinoma (ACC), BLCA, BRCA, LIHC, and LUAD, while it was lower in relatively worse tumor stages in KICH." (PMID 34744715, 2021). "Finally, proteins involved in tumor migration, invasion, malignancy and cell adhesion (Ctsd or Cathepsin D, MTCO2, Tpd52l2, Rab5c, Smarcc1) were also found to be exclusively expressed or significantly up-regulated by the AI tumorspheres compared to the AD cells." (PMID 29298329, 2018).
TPD52L2 also shares sentences with these, for which no sentence is quoted: oral squamous cell carcinoma (5 papers); Breast invasive carcinoma (2); glioblastoma (2); leukemia (2); acute lymphoblastic leukemia (1); Alzheimer disease (1); Bladder Urothelial Carcinoma (1); brain tumors (1); breast tumors (1); colon adenocarcinoma (1); colorectal cancer (1); coronary artery disease (1); Esophageal carcinoma (1); head and neck squamous cell carcinoma (1); inflammatory bowel disease (1); inflammatory myofibroblastic tumor (1); Kidney Chromophobe (1); Lung squamous cell carcinoma (1); lymphoma (1); ovarian serous carcinoma (1); Pan (1); pancreatic cancer (1); prostate adenocarcinoma (1); rectal tumor (1); rectum adenocarcinoma (1); rhabdomyosarcoma (1); Stomach adenocarcinoma (1); uterine cancer (1).